MTOR (mechanistic target of rapamycin kinase)
Diseases named in the same sentence as MTOR in open-access papers (continued):
Sharing a sentence is not in itself a finding about the gene and the disease.
pancreatic cancer (continued). "In a separate study, Leu was found to promote the growth and proliferation of pancreatic cancer cells by stimulating the expression of SESN2 and increasing phosphorylated mTOR (p-mTOR), indicating the involvement of the mTOR signaling pathway in pancreatic cancer development." (PMID 39595578, 2024). "This enrichment supports that Gαi3 might play a crucial role in the Akt-mTOR signaling cascade in pancreatic cancer cells." (PMID 39349432, 2024). "In addition, excitation of PI3K/AKT/mTOR signal channel triggers gemcitabine resistance in pancreatic cancer." (PMID 38555280, 2024). "In another multi-omics study, the integrated analysis of gene copy number alterations, mutations, and proteome expression profiles enabled the identification of two distinct subtypes of pancreatic cancer based on the response to the mTOR (mechanistic target of rapamycin kinase)-targeting drugs." (PMID 39199659, 2024). "Having gained approval for pancreatic cancer treatment, we have suggested that the mTOR inhibitor Rapamycin could be adopted as a potential treatment regimen for oral cancer patients due to its promising effects." (PMID 38276004, 2024). "Furthermore, the PI3K/AKT/mTOR pathway engages in crosstalk with other signaling pathways, including K-Ras and Notch, further contributing to the overall complexity of pancreatic cancer signaling networks." (PMID 39087024, 2024). "In addition, myriad publications showed that the PI3K/mTOR pathway plays an essential role in the tumorigenesis of numerous cancers, including pancreatic cancer." (PMID 37943821, 2023). "Thus, MXRA5-driven pancreatic cancer cell growth is possibly due to, at least in part, by promoting Akt-mTOR signaling." (PMID 36828810, 2023). "Additionally, glycolysis activation in pancreatic cancer can be reversed by an mTOR inhibitor (RAD001), and RAD001 in combination with gemcitabine can promote the chemotherapy sensitivity of PAAD cells." (PMID 37662928, 2023). "Indeed, Akt-mTOR activation was largely inhibited by MXRA5 shRNA or knockout in primary pancreatic cancer cells, but was augmented following ectopic overexpression of MXRA5." (PMID 36828810, 2023). "Therefore, finding new drugs targeting the PI3K-Akt-mTOR path-way will be a prospective therapeutic strategy for pancreatic cancer." (PMID 36864505, 2023). "Akt activation might be more sensitively induced because mTOR is highly activated in pancreatic cancer cells." (PMID 36864505, 2023). "Indeed, Akt-mTOR activation in primary human pancreatic cancer cells was inhibited by MXRA5 shRNA or knockout, but was augmented following MXRA5 overexpression." (PMID 36828810, 2023). "Therefore, targeting translation downstream of mTOR presents a more efficient therapeutic strategy in pancreatic cancer." (PMID 36900235, 2023). "The mammalian target of rapamycin (mTOR)-p65 axis showed sustained activation and was responsible for radiotherapy-induced CXCL8 release, which caused directional migration of NK cells to the TME in patients with pancreatic cancer." (PMID 38264648, 2023). "Additionally, KEGG pathway analysis indicates that DE miRNAs are enriched in several pathways, including the mTOR signaling pathway, Glycerophospholipid metabolism, and Pancreatic cancer." (PMID 37063366, 2023). "In addition, Akt-mTOR activation was also largely inhibited in the MXRA5-depleted pancreatic cancer xenografts." (PMID 36828810, 2023). "However, in pancreatic cancer cells, the main effects of S100a9 are the inhibition of NF-κB and stimulation of mTOR, both of which inhibit autophagy." (PMID 37723445, 2023). "Akt-mTOR activation was also largely inhibited in the MXRA5-depleted pancreatic cancer xenografts." (PMID 36828810, 2023). "While many mTOR inhibitors have been developed and extensively studied in the context of 4EBP1 and cap-dependent translation, the contribution of S6 on translation is still poorly understood in pancreatic cancer." (PMID 36900235, 2023).
pancreatic cancer (continued). "Previous studies have shown that ALKBH1 may participate in the occurrence and development of pancreatic cancer through the mTOR and ErbB signaling pathways as an m1A regulator." (PMID 36550779, 2023). "Indeed, GATA3-AS1-driven tumour growth and metastasis in liver cancer are mediated by GATA3, and NR2F1-AS1 was shown to have adverse effects in pancreatic cancer by activating the NR2F1/AKT/MTOR axis." (PMID 36766730, 2023). "In this study, low expression of mTOR and its phosphorylated form in T-expressing spontaneous liver and pancreatic tumors might account for the dysfunctional effects of T antigen on biosynthesis, which was seen in our investigation." (PMID 35350574, 2022). "Therefore, the role of autophagy in the growth of pancreatic cancer cells mediated by Periplocin through the AMPK/mTOR pathway requires to be investigated." (PMID 35847371, 2022). "In pancreatic cancer, activating mTOR can promote glycolysis and reduce gemcitabine sensitivity." (PMID 36214762, 2022). "Given that suppressing mTOR expression inhibits PNI in pancreatic cancer, we speculated whether mTOR is required for the HGF/c-Met signaling pathway to exert its promoting effects on PNI in pancreatic cancer." (PMID 35449152, 2022). "The well‐demonstrated role of mTOR signaling in diverse human cancers and its regulation controlled by ATF4‐induced TNXIP‐stabilized REDD1 prompted us to examine the potential involvement of ATF4/TXNIP/REDD1/mTOR signaling in GW3965‐induced biological activities in pancreatic cancer cells." (PMID 38089448, 2022). "In addition, dual inhibition of PI3K/mTOR induces overactivation of the MEK/ERK pathway in human pancreatic cancer." (PMID 35203351, 2022). "To determine whether the induction of persisters following mTOR inhibition is a general phenomenon, we treated human pancreatic cancer MIA PaCa-2 cells with a diverse panel of chemotherapeutic agents." (PMID 36396656, 2022). "Moreover, the mTOR pathway was also activated in pancreatic cancer to the promotion of progression and drug resistance." (PMID 36003146, 2022). "Interestingly, the mTOR blocker everolimus can inhibit the Warburg effect by blocking the PI3K/Akt/mTOR signaling pathway, thereby reducing the sensitivity of pancreatic cancer cells to GEM." (PMID 36686732, 2022). "Notably, Rencuzogullari O. and colleagues reported that in pancreatic cancer, palbociclib treatment also acts through the upregulation of this metabolic miRNA, regulating AMPK/mTOR signaling and enhancing pancreatic cancer cell death." (PMID 36498861, 2022). "Both rapamycin (classical autophagy inducer) and RSL3 can block mechanistic target of rapamycin kinase (MTOR) activation and cause GPX4 protein degradation in human pancreatic cancer cells, which can restore or enhance the anticancer activity of gemcitabine in vitro or in xenogeneic PDAC models." (PMID 36105219, 2022). "We investigated the crosstalk between pancreatic cancer cells and nerves after activating mTOR." (PMID 35449152, 2022). "Furthermore, blocking the HGF/c-Met/mTOR signaling pathway by knocking down the expression of mTOR inhibits the invasion and migration of pancreatic cancer cells." (PMID 35449152, 2022). "mTOR is a key regulator in pancreatic cancer glucose metabolism." (PMID 35252207, 2022). "Therefore, inhibition of Akt/mTOR signaling components by myrtucommulone A further suggests its potential for drug development against pancreatic cancer." (PMID 36235333, 2022). "Combined targeting of MEK and mTOR has been successfully applied in several preclinical cancer model systems, leading to potential opportunities to overcome some forms of acquired drug resistance in liver and pancreatic cancers." (PMID 36590793, 2022). "Therefore, in this study, we investigated the effect of Periplocin on autophagy in pancreatic cancer cells and further explored the role of autophagy in the Periplocin's activation of the AMPK/mTOR pathway to inhibit the growth of pancreatic cancer cells." (PMID 35847371, 2022).
pancreatic cancer (continued). "Furthermore, activating the HGF/c-Met/mTOR signaling pathway in pancreatic cancer promotes the growth of DRG axons in the cancer cells-DRG coculture model." (PMID 35449152, 2022). "Furthermore, an inhibitor of the mTOR/4E-BP1 pathway blocked the protein expression of a CAF chemoresistance secretome in pancreatic cancer." (PMID 35884439, 2022). "Furthermore, western blotting revealed that suppressing mTOR expression inhibits the progression of EMT in pancreatic cancer by downregulating the expression of N-cadherin and Vimentin but upregulating the expression of E-cadherin." (PMID 35449152, 2022). "Additionally, knockdown of TRIM32 diminished mTOR/p70S6K activity in pancreatic cancer cells, indicating a positive feedback loop between TRIM32 and mTOR/p70S6K pathway." (PMID 34921503, 2022). "We have previously demonstrated the function of miR-210 as an oncogenic miRNA that mediates chemoresistance to GEM via the protein kinase B/mammalian target of rapamycin (AKT/mTOR) signaling pathway in multiple pancreatic cancer cell lines and in an in vivo animal model." (PMID 33968986, 2021). "In this part, we figured out that PPARγ might regulate mTOR-mediated degradation of ULK1, linked to impaired mitophagy in pancreatic cancer cells." (PMID 35186942, 2021). "Mechanistically, ALKBH1 may participate in the occurrence and development of pancreatic cancer through mTOR and ErbB signaling pathway." (PMID 33779693, 2021). "Furthermore, we demonstrated the involvement of AKT/mTOR signaling in DLEU2L-mediated pancreatic tumor suppression." (PMID 33968986, 2021). "In addition, we used the GDSC database analysis to prove that the mTOR inhibitor (GSK2126458) is very sensitive to pancreatic cancer cell lines, especially for EWSR1.FLI2 and RNF43 mutant." (PMID 34461940, 2021). "In contrast, blockade of PI3K/AKT/mTOR signaling pathway promotes pancreatic cancer cell death." (PMID 34395235, 2021). "Importantly, the tested compounds enhanced the effect of GEM, an approved drug for pancreatic cancer, through apoptosis induction and downregulation of the mTOR pathway." (PMID 33430324, 2021). "Furthermore, periplocin activated AMPK/mTOR to attenuate the proliferation of human pancreatic cancer cells." (PMID 33231372, 2021). "Kaempferol induces ROS-dependent apoptosis in pancreatic cancer cells via TGM2-mediated Akt/mTOR signaling, and TGM2 may represent a promising prognostic biomarker for pancreatic cancer." (PMID 33845796, 2021). "Therefore, our data illustrates that fisetin precisely dampens the PI3K/AKT/mTOR cascade through triggering apoptosis in pancreatic cancer." (PMID 34821587, 2021). "Moreover, we also evaluated the close association between BDNF expression and some critical pancreatic cancer-promoting genes and found that most of these genes were strongly related to BDNF expression in PAAD, including Akt, mTOR, and MAPK." (PMID 34777634, 2021). "Monotherapy targeting of P13k, AKT, and mTOR has not been successful in RAS-mutated pancreatic cancers." (PMID 34901697, 2021). "Moreover, western blotting results showed that NAC alleviated the inhibition of the mTOR signaling pathway, thus protecting pancreatic cancer cells from TEOA-induced ACD." (PMID 34692691, 2021). "Further, our study revealed a mechanism of adipocytic GS-induced chemoresistance in CRC-PC via mTOR activation, in accordance with a precious study showing that Gln-dependent mTOR activation promotes chemoresistance in pancreatic cancer cells in vitro and in vivo." (PMID 34712612, 2021). "Of note, whether the upregulation or scavenging of ROS in pancreatic cancer involves intricate interrelationships among factors involved in Akt/mTOR-induced apoptosis remains controversial." (PMID 33845796, 2021). "Furthermore, the oligomer’s (or CP’s) effect on apoptosis and the mTOR pathway within pancreatic cancer cells was evaluated to dissect the molecular and functional aspects underlying the mechanism of action of such structures." (PMID 33430324, 2021).
pancreatic cancer (continued). "It is well known that the down-regulation of the mTOR pathway inhibits the translation of several RPs, while genome-wide analysis in pancreatic cancer cells have shown that RPs are among the top differentially translated genes upon treatment with mTOR inhibitor." (PMID 34873618, 2021). "Quercetin also regulates apoptosis and autophagy-related pathways and facilitates gemcitabine (an analog of deoxycytidine for DNA synthesis inhibition) chemosensitivity through the receptor involved in advanced glycation end products (RAGE)/PI3K/AKT/mTOR axis in human pancreatic cancer cells." (PMID 34575981, 2021). "This study suggested that the PI3K–Akt signaling pathway may be a key pathway for pancreatic cancer, our study uncovered the potential therapeutic potential of GSK2126458, a specific mTOR inhibitor, for pancreatic cancer." (PMID 34461940, 2021). "Furthermore, it has recently been established that Orai1 inhibition, using the RP4010 CRAC channel inhibitor, decreased pancreatic cancer cell proliferation through the down-regulation of the AKT/mTOR signaling pathway." (PMID 34063470, 2021). "Therefore, we detected the effect of CSE1L on the AKT/mTOR signaling pathways through western blotting in pancreatic cancer cell lines." (PMID 33854580, 2021). "This combotherapy of N6L and mTOR inhibitors could constitute a promising alternative to treat pancreatic cancer." (PMID 34638443, 2021). "In summary, the results of our present study indicate that kaempferol induces ROS-dependent apoptosis in pancreatic cancer cells via TGM2-mediated Akt/mTOR signaling, and TGM2 may represent a promising prognostic biomarker for pancreatic cancer." (PMID 33845796, 2021). "Overexpression of KLK8 might promote proliferation and inhibit apoptosis via epidermal growth factor (EGF) signaling-dependent activation of PI3K/Akt/mTOR pathway in pancreatic cancer cells." (PMID 34395235, 2021). "Considering the previously analyzed results of apoptosis, these observations signify that DLEU2L overexpression or miR-210-3p interference promoted pancreatic cancer cell death by inhibiting AKT/mTOR activation, and the effects are more prominent at higher GEM concentrations." (PMID 33968986, 2021). "Evr treatment may be a promising strategy to target the growth and activity of GEM-resistant pancreatic cancer cells by regulating glucose metabolism via inactivation of PI3K/AKT/mTOR signaling." (PMID 33849427, 2021). "Furthermore, a simultaneous therapy of mechanistic target of rapamycin kinase (mTOR) inhibitor with GANT61 was confirmed as a more effective treatment for pancreatic cancer by inhibition of the stemness of pancreatic cancer stem cells." (PMID 33898430, 2021). "Here we found that PCK1 is important for Akt-mTOR activation in pancreatic cancer cells." (PMID 34620839, 2021). "Over 90% of pancreatic cancers are known to harbor activating KRAS mutations and the other 10% have oncogenic fusions, BRAF mutations, Receptor Tyrosine Kinase (RTK) mutations/amplifications, or AKT/mTOR activation." (PMID 34504655, 2021). "We hypothesized that TGM2 serves as a target of kaempferol to facilitate apoptosis, which may be correlated with ROS-dependent Akt/mTOR signaling in pancreatic cancer." (PMID 33845796, 2021). "Moreover, the PCK1-S90A suppressed Akt-mTOR activation and inhibited pancreatic cancer migration and proliferation." (PMID 34620839, 2021). "This investigation was aimed at disclosing whether SRPX2 affected pancreatic cancer (PC) chemoresistance by regulating PI3K/Akt/mTOR signaling." (PMID 33336063, 2020). "Based on all above data, we speculated that betulinic acid may specifically inhibit mTOR signaling via inducing apoptosis in pancreatic cancer." (PMID 32513155, 2020). "l-Leucine promoted the proliferation and clone formation of PANC-1 cells in our study, and the mechanism may be that through this pathway, the inhibition of mTOR reduced, thus promoting the growth of pancreatic cancer cells." (PMID 33343350, 2020).
pancreatic cancer (continued). "Research demonstrated that the upregulation of METTL14 expression in pancreatic cancer cells could reduce the response to mTOR signal-mediated autophagy after cisplatin treatment." (PMID 32760220, 2020). "In conclusion, these findings suggest that Sestrin2 may promote the occurrence and development of pancreatic cancer through mTOR signaling." (PMID 33343350, 2020). "Nevertheless, the exact molecular mechanism of mTOR signaling regulated by betulinic acid in pancreatic cancer remains unclear." (PMID 32513155, 2020). "In addition, MFN2 decreased the levels of phospho-phosphoinositide 3-kinase (p-PI3K), phospho-protein kinase B (p-Akt), and phospho-mammalian target of rapamycin (p-mTOR) proteins, which promote pancreatic cancer cell growth, proliferation, and metastasis." (PMID 33233365, 2020). "Previous studies showed that loss of tumor suppressor, PTEN, and subsequent activation of PI3K/AKT/mTOR pathway may lead to accumulation of CE in advanced pancreatic cancer." (PMID 31978092, 2020). "Furthermore, the KEGG pathway analysis revealed that the largest subset of differentially expressed genes was associated with pancreatic cancer, and with the VEGF, mTOR, and insulin signaling pathways." (PMID 32843065, 2020). "To further investigate the influence of ERSD on the PI3K/AKT pathway, which was predicted to be suppressed in comparison to control diet, we assessed the activation status of PI3K, AKT, mTOR, and p70S6K in pancreatic cancer tissues from both experimental groups." (PMID 33383727, 2020). "However, here we observed higher mTORC1/2 formation in PCS generated from both the cell lines as depicted by the elevated phosphorylation of mTOR both at the serine 2448 and 2481 positions, respectively, compared to adherent pancreatic cancer cells." (PMID 32575925, 2020). "In our previous research, we found that L-type amino acid transporter 2 (LAT2), an oncogenic protein in pancreatic cancer cells, could Gln-dependently activate mTOR to inhibit apoptosis and promote glycolysis." (PMID 32122374, 2020). "Similarly, suppression of CAF mediated secretion of IL-6 by inhibiting mTOR pathway via somatostatin analogue reversed the chemoresistance in pancreatic tumor." (PMID 30680600, 2019). "The results from both in vitro and in vivo experiments suggested that DTLL enhanced DNA damage via EGFR/HER2‐dependent blockage of PI3K/AKT/mTOR and PD‐L1 signaling pathways in cancer cells, leading to the inhibition of cell proliferation and immunosurveillance escape from pancreatic tumor." (PMID 30681288, 2019). "Inhibition of mTOR in patient-derived pancreatic cancer xenografts was comparable to patient response to mTOR inhibitors, but surprisingly could not be predicted by screening for pathway activation." (PMID 31398893, 2019). "Phosphorylation of Extracellular regulated protein kinases 1/2 (ERK1/2) and mTOR was inhibited and pancreatic tumor size was reduced in mice if the engrafted pancreatic tumor cells were cultured in engineered-resistant starch, which can shape the composition of the gut microbiomes." (PMID 31785619, 2019). "mTOR inhibition by rapamycin has been reported to decreased pancreatic cancer stem cell population." (PMID 30441806, 2018). "We also assessed the role of mTOR in the GEM sensitivity of pancreatic cancer cells." (PMID 30419950, 2018). "Additionally, we found that orexin-A treatment can promote cell proliferation through inhibiting Akt/mTOR-mediated apoptosis in pancreatic cancer PANC1 cells." (PMID 30429828, 2018). "Therefore, orexin-A can regulate apoptosis to promote cell proliferation through activating theAkt/mTOR signaling pathway in pancreatic cancer." (PMID 30429828, 2018). "Then, we investigated whether the process by which LAT2 targets mTOR activation to regulate apoptosis, glycolysis and chemosensitivity in pancreatic cancer cells was dependent on glutamine." (PMID 30419950, 2018).